MALAT1 (metastasis associated lung adenocarcinoma transcript 1)
Diseases named in the same sentence as MALAT1 in open-access papers (continued):
Sharing a sentence is not in itself a finding about the gene and the disease.
cervical carcinoma (continued). "For example, Metastasis-associated lung adenocarcinoma transcript 1 (MALAT1), which is excessively expressed in cancer tissues and cervical cancer cells infected with “high risk” HPV, interacts with several serine-arginine proteins, namely SRSF1, SRSF2, SRSF3 and SRSF5." (PMID 36144454, 2022). "In addition, the expression of miR-145 was negatively correlated with MALAT1 expression in cervical cancer tissues." (PMID 35692795, 2022). "Thus, we concluded that the LncRNA MALAT1 expression level is negatively related to miR-124, implying their regulatory relationship in the progression of cervical carcinoma." (PMID 34221014, 2021). "Thus, we subsequently examined LncRNA MALAT1 and miR-124 by real-time PCR in cervical carcinoma tissue compared with its paracarcinoma tissue, as well as in mice tumor tissues." (PMID 34221014, 2021). "MALAT1 promotes DDP resistance in cervical cancer through activation of the PI3K/AKT pathway." (PMID 34853725, 2021). "Recently, it was reported that lncRNA-MEG3 served as a cancer suppressor via lessening the expression of miR-21 in cervical cancer; MALAT1 increased cell colony formation and cell cycle regulation and suppressed cell apoptosis through sponging miR-145 in cervical cancer." (PMID 34221014, 2021). "Our findings suggest that MALAT1 could be recognized as a potential target to improve clinical effects in the progression of cervical carcinoma." (PMID 34221014, 2021). "Moreover, MALAT1 was also overexpressed in HPV16 positive cervical cancer cell lines in an HPV16 E7 dependent manner." (PMID 34659524, 2021). "Two other lncRNAs were involved in cell cycle regulation in cervical cancer: MALAT1 and NEAT1." (PMID 32585857, 2020). "In cervical cancer, the lncRNA MALAT1 regulates apoptosis by influencing the expression of caspase 3, caspase 8, Bcl2, Bax and Bcl-xL, and additionally enhances cell invasion and metastasis by upregulating the expression of Snail and affecting the epithelial–mesenchymal transition." (PMID 32607313, 2020). "MALAT1 promotes the chemo-resistance of cervical cancer via BRWD1-PI3K/AKT pathway." (PMID 32591022, 2020). "The miRNA sponge function of MALAT1 was also reported for cervical cancer." (PMID 29147648, 2017). "Additionally in cervical cancer, higher levels of MALAT1 are found in cancer tissues compared to normal cervix and are associated with a poor prognosis." (PMID 28637507, 2017). "Since PCDH10 is also silenced in cervical carcinoma, it could be of interest to investigate whether MALAT1 regulation and its effects are somewhat similar in different malignancies." (PMID 28637507, 2017). "This suggested that MALAT1 was activated in cervical cancer and may have an important role in tumorigenesis." (PMID 24932303, 2014). "Exosomal MALAT1 may become a promising therapeutic target for treating cervical cancer." (PMID 36793374, 2023). "Similarly, MALAT1 promoted cisplatin resistance in cervical cancer, which might be attributed to the inhibition of apoptosis by activating the PI3K/AKT pathway." (PMID 36793374, 2023). "Similarly, exosomal lncRNAs, including Hox transcript antisense intergenic RNA (HOTAIR), metastasis-associated lung adenocarcinoma transcript 1 (MALAT1), and maternally expressed gene 3 (MEG3), are predominantly observed in cervical cancer–derived exosomes in cervicovaginal lavage samples." (PMID 31438991, 2019). "Furthermore, studies on exosome-derived lncRNAs in vaginal lavage specimens revealed that the expression of HOTAIR, metastasis associated lung adenocarcinoma transcript 1 (MALAT1), and maternally expressed 3 A (MEG3A) in cervical cancer patients and healthy samples were significantly different." (PMID 29558960, 2018). "Therefore, MALAT1 may be a potential screening and therapeutic target for the treatment of cervical cancer." (PMID 24932303, 2014).
cervical carcinoma (continued). "A multi-analyte detection model integrating HOTAIR, MALAT1, and MEG3 expression patterns achieves high-precision stratification of cervical cancer patients, HPV-persistent carriers, and healthy controls." (PMID 40809518, 2025). "Overexpression of HPV-16 E7 increases MALAT1 when transfected into HPV-negative HEK-293T and C33A cells, and E7 knockdown in the human cervical carcinoma lines CaSki and SiHa results in decreased MALAT1 expression." (PMID 37509353, 2023). "Silencing of MALAT1 increased the expression of cleaved caspase-3, while upregulation of MALAT1 increased the mRNA level of BRWD1 and elevated the expression of p-PI3K and p-Akt in cervical cancer cells." (PMID 36438563, 2022). "After sorting the data, we selected MEG3, TIMP3, DAPK1, and SOX1 as being the most hypermethylated genes specific for the incipient stages of cervical carcinoma, while MLH1 and MALAT1 were chosen as the most hypomethylated genes." (PMID 35682732, 2022). "Additionally, our research proposed the consideration whether specifically inactivating MALAT1 expression in cervical tumor via gene engineering tools could ameliorate mortality and morbidity of cervical carcinoma, or other cancers, providing more beneficial effects to improve the outcomes." (PMID 34221014, 2021). "In cervical cancer, HOTAIR and MALAT1 were upregulated and MEG3 was downregulated within the cervicovaginal lavage in cervical cancer patients." (PMID 34067896, 2021). "It was found miR-124 inhibited cell viability and invasion of HR-HPV-positive cervical cancer cells by targeting RBG2, which was regulated by lncRNA MALAT1." (PMID 33040049, 2020). "Also several lncRNAs, comprising among others HOTAIR, MALAT1, GAS5, and MEG3, have shown to be associated with various pathogenic processes such as tumor progression, invasion as well as therapeutic resistance and emerged as new diagnostic and prognostic biomarkers in cervical cancer." (PMID 32154165, 2020). "Our previous study has shown that metformin disrupts the sponge effect of long non-coding RNA MALAT1/miR-142-3p to activate the expression of the downstream antitumor protein high-mobility group A protein 2 (HMGA2) and exert an anti-cervical cancer effect." (PMID 32631421, 2020). "Some of the studies cited in the tables above implicated E6 and/or E7 as regulators of certain lncRNAs, including PVT1, MALAT1, SNHG12, lnc-CCDST, LINC01101 and LINC00277 by depleting E6/E7 expression in cervical cancer lines." (PMID 32326624, 2020). "Ectopic expression of MALAT1 induced an increase in CKS1 in ESCC cells and decrease in miR-145 in cervical cancer cells, and which is leading to inhibition of cancer cell apoptosis after radiation treatment." (PMID 28872613, 2017). "LcnRNAs of HOTAIR, CCAT2, MALAT1, EBIC and MEG3 have been reported to be involvled in cervical cancer metastasis." (PMID 27736969, 2016). "Further studies are required to analyze the molecular mechanisms of MALAT1 in cervical tumorigenesis, using more clinical samples to further analyze the correlation among MALAT1, HPV and cervical cancer progression." (PMID 24932303, 2014). "Radiation exposure leads to the overexpression of MALAT-1 and the reduction of miR-145 levels; however, the downregulation of MALAT-1 and the overexpression of miR-145 can sensitize cervical cancer cells to radiation by inducing apoptosis and regulating the G2/M phase." (PMID 38651153, 2024). "The expression levels of MALAT-1 between samples of different cancers and normal patients show that high expression of MALAT-1 is a prevalent event in various tumors such as ESCC, HCC, cholangiocarcinoma, cervical cancer (CC), sarcoma, and melanoma." (PMID 38201661, 2024). "In addition, MALAT1 can activate PI3K/AKT pathway and promote cisplatin resistance in cervical cancer." (PMID 36793374, 2023).
cervical carcinoma (continued). "Using a specific siRNA targeting MALAT1 in HPV-positive cells, the results obtained showed that downregulation of MALAT1 significantly suppressed the proliferation of the two HPV-positive cervical cancer cell lines." (PMID 37639643, 2023). "Collectively, these results demonstrated that MALAT1 may promote the proliferation and metastasis of HPV-positive cervical cancer cell in vitro." (PMID 37639643, 2023). "In addition, MALAT1, PVT1, H19, and XIST can promote cancer cell proliferation, invasion, and migration and play a role in the progression of cervical cancer." (PMID 35262965, 2022). "The results revealed HOTAIR, MALAT1 and MEG3 in cervical cancer patients was higher than that in healthy patients, indicating that lncRNA HOTAIR, MALAT1 and MEG3 levels in the exudates of vaginal lavage fluid samples have the potential of being the biomarkers for early diagnosis of cervical cancer." (PMID 34370713, 2021). "Also, the key role of LncRNAs on cervical carcinoma has been addressed, including PTCSC3, NEAT1, UCA1, and MALAT1." (PMID 34221014, 2021). "Furthermore, MALAT1 promoted EMT via increasing Snail in cervical tumor cells, implying the aggregating effect of MALAT1 on cervical carcinoma." (PMID 34221014, 2021). "Exosomal lncRNA MALAT1, HOTAIR, and MEG3 are differentially expressed in cervical cancer cervicovaginal lavage samples, which suggests that these lncRNAs can be promising biomarkers in detecting cervical cancer." (PMID 31360701, 2019). "Similarly, LncRNA MALAT1 and HOTAIR were reported to predict the poor clinical outcome of patients with cervical cancer." (PMID 29720427, 2018). "MALAT1 was upregulated in esophageal squamous cell carcinoma (ESCC) and cervical cancer tissues." (PMID 28872613, 2017). "The results indicated that MALAT1 is expressed in cervical cancer but not in normal epithelial cells, and further study in normal cervical cell samples also demonstrated this." (PMID 24932303, 2014). "Furthermore, due to the established link between cervical cancer and HPV infection, elucidating the correlation among MALAT1, HPV and cervical cancer warranted further investigation." (PMID 24932303, 2014). "However, in cisplatin resistance in cervical cancer, the role of MALAT1/miR-370-3p role is not expounded." (PMID 36793374, 2023). "MALAT1 was expressed in all cervical cancer cell lines but not in HaCaT cells and normal samples." (PMID 24932303, 2014). "Due to limited funding, the interactions between MALAT1 and ALKBH5, as well as the m6A methylation level in HPV-positive cervical cancer or clinical patient samples, were not evaluated in this study." (PMID 37639643, 2023).
lung adenocarcinoma (92 papers, 2013 to 2025). A carcinoma that arises from the lung and is characterized by the presence of malignant glandular epithelial cells. "This study aimed to explore the role of long non-coding RNAs metastasis-associated lung adenocarcinoma transcript (lncRNA MALAT1), and its underlying mechanisms in hypopharyngeal squamous cell carcinoma (HSCC)." (PMID 39319867, 2025). "The initial discovery of metastasis-associated lung adenocarcinoma transcript 1(MALAT1) was made in human lung adenocarcinoma, and later investigations have demonstrated its presence in other tissue types." (PMID 38577023, 2024). "Distribution frequency of MALAT1 genotypes of patients with lung adenocarcinoma and multiple logistic regression analysis of EGFR mutation association." (PMID 38517388, 2024). "We initially designed a series of PS-modified 20-mer ASOs targeting metastasis associated in lung adenocarcinoma transcript-1 (Malat1) RNA." (PMID 38978695, 2024). "In contrast, a survival cohort analysis depicting the SNP rs3200401 of MALAT1 was associated with advanced lung adenocarcinoma." (PMID 37526759, 2023). "For example, metastasis-associated lung adenocarcinoma transcript 1 (MALAT1) has been widely studied in cancer lung adenocarcinoma." (PMID 37283796, 2023). "Metastasis associated in lung adenocarcinoma transcript (MALAT1) is one of the first discovered lncRNAs that was identified during a screening of genes associated with lung adenocarcinoma." (PMID 36675533, 2023). "Daily HS intake modified aortic renovation by enhancing the antioxidant capacity, restraining hypertrophy and fibrosis, downregulation of the metastasis associated lung adenocarcinoma transcript (MALAT1), and cyclophilin A (CyPA)/ERK1/2 levels." (PMID 37415906, 2023). "This contrasted with metastasis-associated lung adenocarcinoma (MALAT1) lncRNA that is normally highly associated with nuclear speckles, which was released and dispersed in the nucleoplasm." (PMID 35741072, 2022). "Metastasis-associated lung adenocarcinoma transcript 1 (MALAT1) was the first lncRNA with a designated role in lung adenocarcinoma." (PMID 34681797, 2021). "Metastasis associated in lung adenocarcinoma transcript (MALAT1), which is an abundant and highly conserved lncRNA across mammals, is stabilized by forming a triple helix structure at its 3′ end." (PMID 33435206, 2021). "The MALAT1 ncRNA (~8000 nucleotides) was originally found as a metastasis-associated lung adenocarcinoma transcript 134, and it is overexpressed in various kinds of cancers." (PMID 32047236, 2020). "The lncRNA metastasis-associated lung adenocarcinoma transcript 1 (MALAT1) was first reported to be overexpressed in lung adenocarcinoma." (PMID 31847392, 2019). "MALAT1 (metastasis-associated lung adenocarcinoma transcript 1) is firstly found to be positively correlated with metastasis in lung adenocarcinoma, which is located on 11q13.1 and is 8545 nt in length." (PMID 29535782, 2018). "The first identified lncRNA is a gene associated with lung adenocarcinoma and designated as metastasis-associated lung adenocarcinoma transcript 1 (MALAT1) in respiratory diseases." (PMID 29197377, 2017). "We further analyzed the associations of MALAT1 rs3200401 with survival outcomes among advanced patients with lung adenocarcinoma and squamous cell carcinoma separately." (PMID 28253859, 2017). "One such example of this “m6A switch” behavior within the local RNA structure is found in the human metastasis-associated lung adenocarcinoma transcript (MALAT1); here, a portion of MALAT1 forms a 30-nucleotide stem loop containing the GGACU m6A methylation motif in a dsRNA region." (PMID 37501707, 2023). "Furthermore, the lncRNA MALAT1 (metastasis associated lung adenocarcinoma transcript 1), originally described in lung adenocarcinoma, is also expressed in the kidneys." (PMID 30909482, 2019).
lung adenocarcinoma (continued). "The rs3200401 T allele located on the lncRNA MALAT1 was associated with a better survival for advanced lung adenocarcinoma patients, which may offer a novel prognostic biomarker for this patient subgroup." (PMID 28253859, 2017). "To give a clue for further interpretation and explanation of the biological function of rs3200401, we still analyzed the TCGA data and found that a higher MALAT1 expression level was associated with a worse survival outcome among advanced lung adenocarcinoma patients." (PMID 28253859, 2017). "The MALAT1 rs3200401 T allele may serve as a novel biomarker for predicting clinical outcomes of lung adenocarcinoma." (PMID 28253859, 2017). "A previous study suggests that MALAT1 overexpression can drive tumor progression with a lesser impact on tumor growth in lung adenocarcinoma." (PMID 38791954, 2024). "In lung adenocarcinoma A549 cells that are resistant to Gefitinib, MALAT-1 expression was significantly higher than in normal cells." (PMID 38201661, 2024). "This study aims to explore the relationship between MALAT-1 and miR-125 and investigate their involvement in molecular targeted therapy and drug resistance mechanisms in lung adenocarcinoma." (PMID 39196297, 2024). "siRNAs against MALAT1 display a 2-fold decrease in the MALAT1 level, and its knockdown results in reduced cell migration in lung adenocarcinoma." (PMID 38338910, 2024). "MiR-429 is a tumor suppressor, and its expression was inversely correlated with MALAT-1 expression in lung adenocarcinoma." (PMID 38201661, 2024). "MALAT1 rs3200401 genotype distribution and clinicopathologic characteristics of lung adenocarcinoma patients." (PMID 38517388, 2024). "This assay proves that overexpression of MALAT-1 can augment the drug resistance of lung adenocarcinoma cells to erlotinib, while knockout of MALAT-1 can enhance the drug sensitivity." (PMID 39196297, 2024). "MALAT1 has also been shown to induce up-regulation of the EMT phenotype in lung adenocarcinoma, to the extent that several authors have attributed to MALAT1 a potential value as a target for potential targeted therapies." (PMID 38283359, 2023). "MALAT1 (metastasis-associated lung adenocarcinoma transcript 1, also known as NEAT2 or nuclear enriched abundant transcript 2) is directly correlated with the aggressiveness and mortality of lung adenocarcinoma." (PMID 36077530, 2022). "The MALAT1 gene was first discovered in lung adenocarcinomas and reported to be a crucial factor in several human diseases, such as tumors, cardiovascular disease, and pulmonary arterial hypertension." (PMID 35392816, 2022). "MALAT1 is an intergenic lncRNA that was first discovered as a prognostic biomarker for patient survival of stage I lung adenocarcinoma." (PMID 33670447, 2021). "In vivo and in vitro experiments showed that MALAT1 promoted epithelial–mesenchymal transition and metastasis of lung adenocarcinoma cells." (PMID 34956340, 2021). "MALAT-1 has been associated with metastasis in NSCLC and is known as a poor prognostic marker for survival in lung adenocarcinoma." (PMID 30012957, 2018). "In lung adenocarcinoma cells, MALAT-1 was also reported enhancing cell motility by affecting the expression quantity of motility-related genes." (PMID 30285605, 2018). "MALAT-1 is a 7 kb long non-coding nuclear RNA, which is over-expressed in lung adenocarcinoma and other NSCLC cells." (PMID 30012957, 2018). "We found significant higher MALAT1 expression levels in lung adenocarcinoma tissues than in lung squamous cell carcinoma tissues (P <0.001)." (PMID 28253859, 2017). "We found that among advanced lung adenocarcinoma patients, those carrying MALAT1 rs3200401 CT or CT + TT genotypes had significant longer survival time and decreased death risks than those carrying rs3200401 CC genotype." (PMID 28253859, 2017).